INS (insulin)
Diseases named in the same sentence as INS in open-access papers (continued):
Sharing a sentence is not in itself a finding about the gene and the disease.
Hypoglycemia (continued). "Furthermore, to achieve a lower HbA1c level might be accompanied with more episodes of hypoglycemia, especially for patients with insulin administration." (PMID 35023626, 2022). "As this mechanism is independent of the action of insulin, they rarely cause hypoglycemia." (PMID 36457541, 2022). "The results of this systematic review are in line with those from studies in adults with T1D, in showing that a pre-prandial bolus provided better post-prandial glycemia and HbA1c without increasing the risk of hypoglycemia, and without affecting total daily insulin dose and BMI." (PMID 36556278, 2022). "Finally, high sugar intakes from soft drinks could induce hypoglycemia through a higher insulin response and thereby affects hormone secretion and potentially mood states." (PMID 35215425, 2022). "However, a serious concern regarding insulin is drug-induced hypoglycemia." (PMID 35343912, 2022). "However, personal CGM with real-time alerts might benefit patients with ESKD on complex insulin regimens or vulnerability to hypoglycemia." (PMID 35528010, 2022). "However, the fear of hypoglycemia resulting from the combination of insulin with SGLT2i or GLP-1 RA may lead to the underprescription of these agents in patients using insulin." (PMID 36408008, 2022). "The HARPdoc model may have relevance outside insulin-driven hypoglycaemia." (PMID 35484106, 2022). "This “functional hypercortisolism” by antagonizing insulin actions may prevent hypoglycemia." (PMID 35897752, 2022). "Some researchers are considering the impact of somatostatin antagonists or agents that suppress somatostatin secretion that could be used along with insulin therapy to restore a more appropriate release of glucagon during hypoglycemia and postprandial or fasting conditions." (PMID 36992764, 2022). "In clinical analysis, insulin detemir declined hemoglobin A1C (Hb AIC) to a specific extent of 7.0% for 70% of subjects such as human basal insulin NPH, and may cause a low rate of hypoglycemia in patients with TIDM and TIIDM." (PMID 35723344, 2022). "However, occasional cases of hypoglycaemia have been reported in Px-treated patients, raising the possibility that Px may also increase sensitivity to insulin." (PMID 36289640, 2022). "If the mealtime insulin bolus is given later, this may cause over-delivery of insulin and subsequent hypoglycemia if the closed-loop directed insulin is not taken into consideration." (PMID 32914648, 2022). "Interestingly, insulin treatment significantly increased eNOS expression in the hypoglycemia groups compared with DM (p < 0.05), and expression was higher in the RH-DM than in the H-DM group (DM 0.54-, H-DM 1.13-, and RH-DM 1.76-fold compared with controls; p < 0.05)." (PMID 35915611, 2022). "In addition, our low incidence of hypoglycemia may be due to incremental increases in insulin administered (commencing at daily s.c. injections of 2.5U insulin) and intact counter-regulatory compensatory responses in these animals." (PMID 35269778, 2022). "The mechanism of dapagliflozin is to promote glycemic disposal in an insulin-independent way, thereby decreasing postprandial glycemia and glycemic excursions accompanied by an inferior insulin demand without increasing the risk of hypoglycemia." (PMID 35872994, 2022). "Similarly, elevated insulin levels, in the absence of hypoglycemia, are also associated with reduced GH levels." (PMID 35544473, 2022). "Postprandial hypoglycemia due to an exaggerated insulin response following a high sugar intake, as well as the addiction-like effects of sugars influencing dopaminergic neurotransmission mechanisms, may also provide an explanation about the link between high sugar intake and low mood." (PMID 35228922, 2022).
Hypoglycemia (continued). "Thus, it needs a reliable control algorithm to combine multiple hypoglycemia prevention procedures such as initiation of glucagon when the blood glucose reaches the threshold (50–90 mg/dL), suspension and control insulin delivery, and escalation of alarms to remind the user." (PMID 36411933, 2022). "The hypoglycemia in the insulin-treated patients may be having an adverse effect." (PMID 35629267, 2022). "Another study observed that phenolic compounds of stevia (stevioside and steviol) could alone increase the secretion of insulin in intestinal (INS) pancreatic β‐cell that helps to reduce BGL without increasing the risk of hypoglycemia." (PMID 36171777, 2022). "However, there are descriptions that hypoglycemia may remarkably occur in 36% of patients with CACNA1C-associated Timothy syndrome, further suggesting a role of CACNA1C for human insulin secretion and blood glucose regulation." (PMID 35897673, 2022). "Nutrient ingestion, particularly if given through a gastrostomy, in children who underwent Nissen Fundoplication leads to rapid increase in plasma glucose as well as plasma insulin followed by hypoglycemia; this may be, in part, due to exaggerated GLP-1 secretion." (PMID 35399928, 2022). "β-cell nucleus hypotrophy could be caused by the down-regulated endogenous insulin production through decreased transcriptional activity, as reduced pancreatic pro- and prepro-insulin mRNA and insulin levels accompanies 5, 6, 12, and 28 days of insulin-induced hypoglycaemia in rats." (PMID 35982111, 2022). "Meanwhile, the proband’s serum glucose, insulin (INI), C-peptide (CPS), and pro-insulin (pro-INS) levels were tested, and the results showed that glucose was decreased while the insulin level was either in the normal reference range or increased at the time of the hypoglycemia." (PMID 35255927, 2022). "Furthermore, IV administration of naloxone restored LH pulses that were suppressed by insulin-induced hypoglycemia in OVX ewes, and IV injections of naloxone restored LH pulses that were suppressed by the administration of an endotoxin lipopolysaccharide in OVX heifers and OVX rhesus monkeys." (PMID 36033602, 2022). "The risk of hypoglycaemia is low as the effect of SGLT-2 inhibitors does not depend on insulin." (PMID 35684097, 2022). "Therefore, there were some conflicts in judging about the SCT side effects in these trials, and it was decided to omit the hypoglycemia because it could occur due to the insulin therapy and thyroid autoimmune disorder along with T1DM without any intervention." (PMID 35501872, 2022). "Although insulin therapy decreased the danger of late-diabetic complications by reducing the average blood glucose, the treatment could result in an elevated occurrence of hypoglycemia in T1DM." (PMID 36572938, 2022). "Furthermore, independent of causality, reducing the risk of any hypoglycaemia by lifestyle intervention or pharmacological solutions will benefit individuals using insulin, including those at high cardiovascular risk." (PMID 34704120, 2022). "Whether the drop in glucose levels itself leads to copeptin secretion, or whether it mirrors other stimuli such as hypoglycemia-induced stress cannot be answered with our study and could be better defined in further research measuring glucagon and insulin levels throughout the stimulation tests." (PMID 35723775, 2022). "Information about PA (time of day, duration, and type), hypoglycemia occurring before bedtime, and mitigation strategies (e.g. insulin dosage and CHO intake modulations) to reduce the risk of nocturnal hypoglycemia were based on the participants’ self-reported data in their logbook." (PMID 36237197, 2022). "While the total daily dose of insulin was reasonable at 0.61 unit/kg, patients tended to have basal-heavy regimens and might have benefited from a dose reduction at discharge to further reduce the frequency of hypoglycemia." (PMID 35881437, 2022).
Hypoglycemia (continued). "The faster-acting insulin Aspart has an earlier onset of action than insulin Aspart, which should provide better control of the postprandial state without increasing the risk of hypoglycemia." (PMID 36014822, 2022). "In addition, it was further shown that epinephrine and norepinephrine levels progressively increased with increasing doses of insulin, suggesting that insulin also plays a direct role in stimulating release and effects of catecholamines to prevent hypoglycemia in dogs." (PMID 35897752, 2022). "Given that the women attended the HNU, following an overnight fast, we expect that any hypoglycaemia over the period may have initiated a decrease in insulin secretion with a corresponding increase in glucagon to increase hepatic EGP via glycogenolysis and gluconeogenesis." (PMID 36584200, 2022). "However, the C-peptide concentration is almost always elevated at the time of hypoglycemia and this surrogate marker could be a better indication of dysregulated insulin secretion than serum insulin itself." (PMID 35296370, 2022). "In addition, t he association of degree of NAFLD with the incidence of severe hypoglycemia was lower in those who used insulin compared with those who did not." (PMID 35195697, 2022). "There was a substantially lower risk (HR 0.18, 95% CI 0.08–0.49) of incident hypoglycaemia with IDegLira versus ICT in our real-world study, which was somewhat lower than the estimated risk ratio of 0.39 (95% CI 0.29–0.51) for IDegLira versus basal–bolus insulin reported in DUAL VII." (PMID 36104712, 2022). "We suggest that it might be helpful to employ continuous glucose monitoring in future studies aiming at the optimization of basal insulin titration algorithms, which should help to identify the role of low plasma glucose concentrations or hypoglycemia as a barrier to increasing insulin doses." (PMID 35942330, 2022). "Since metformin does not directly stimulate insulin secretion, its hypoglycemia risk is small." (PMID 36595813, 2022). "In childhood, the most common cause of hypoglycemia is represented by Congenital Hyperinsulinism (CH), a heterogeneous congenital disorder characterized by a dysregulation in insulin secretion which results in random hypoglycemia associated with low or normal ketones and no metabolic acidosis." (PMID 36619556, 2022). "Thus, during insulin-induced hypoglycemia, glucagon secretion is increased due to GIP use." (PMID 35630534, 2022). "Interestingly, the risk of hypoglycemia does not increase in patients using both insulin and metformin." (PMID 35324747, 2022). "Furthermore, they believe that most of their patients could refuse insulin, and about half of the PCPs (46.5%) reported delaying insulin due to their own fear of hypoglycemia." (PMID 36554673, 2022). "In addition, 30w old Nkcc1βKO mice developed resistance to insulin-induced hypoglycemia." (PMID 36580474, 2022). "Therefore, postpartum insulin dosage should reduce timely to avoid hypoglycemia." (PMID 36339424, 2022). "These conclusions coincide with the ones generated by our tool in that overall IGlar is superior to NPH insulin, in particular with respect to safety and in reducing the risk of nocturnal hypoglycemia, but not superior in efficacy in terms of the reduction of HbA1c levels." (PMID 35659056, 2022). "Moreover, a survey including physicians worldwide found that if the risk of hypoglycemia was not a concern, most clinicians (75.5%) would be more relaxed in the intensification of insulin therapy." (PMID 35457303, 2022). "C-peptide measurement is critical in insulin selection for it can reflect islet function of patients, the regimen for patients who use premixed insulin could be considered to use basal insulin if they present higher incidence of hypoglycaemia, greater GV and better islet function." (PMID 35574003, 2022).
Hypoglycemia (continued). "Moreover, insulin injections and the AEs of blood sugar lowering agents (e.g., hypoglycemia, SGLT-2 inhibitor-induced UTI/genital infection, and metformin-induced gastrointestinal symptoms) may also be associated with pain and discomfort." (PMID 34946402, 2021). "Thus, hydroxychloroquine therapy in COVID-19 may lead to hypoglycemia since this drug reduces insulin degradation and improves insulin storage with augmentation of peripheral glucose metabolism." (PMID 34124187, 2021). "Thus, the attenuated inhibition of parasympathetic activity observed in overweight and insulin-resistant individuals during hypoglycaemia may potentially enhance the defence against hypoglycaemia and the maintenance of elevated everyday glucose levels." (PMID 33241460, 2021). "Therefore, we also tested the hypothesis that C-peptide infusion would enhance glucagon secretion and HGP in response to insulin-induced hypoglycemia." (PMID 34003799, 2021). "This retrospective cohort study indicated that among persons with T2DM and compensated liver cirrhosis, insulin users were associated with higher risks of death, liver-related complications, cardiovascular events, and hypoglycemia compared with insulin nonusers." (PMID 34118892, 2021). "Finally, a role was suggested for closed-loop glucose control systems and immunomodulatory treatment options, to avoid hypoglycemia during insulin therapy and to control the rise in circulating cytokine levels in diabetic patients with severe sepsis and septic shock." (PMID 33973089, 2021). "Subsequently, the DEVOTE trial demonstrated that, among insulin-naïve T2D patients at high risk for cardiovascular events, degludec was noninferior to glargine with respect to the incidence of MACE, but was associated with significantly lower rates of severe hypoglycemia." (PMID 34774054, 2021). "Thus, insulin indeed may be cognitively neutral; however, further research is needed to clarify if hypoglycemia may balance out some cognitive protection, especially in a region with frequent insulin usage." (PMID 34857046, 2021). "This indicated that telmisartan might be applied as an insulin secretagogue without the risk of hypoglycemia." (PMID 34594226, 2021). "Thiazolidinediones have been found to improve insulin sensitivity without causing hypoglycemia in their roles as PPARγ agonists, leading to an A1c decrease of 0.5–1.4%, and these drugs, which are metabolized by the liver, are used to treat chronic kidney disease." (PMID 34203830, 2021). "However, the reduced risks of hospitalized hypoglycemia and all-cause mortality associated with the use of a GLP-1RA versus insulin may lead to a favorable cost-utility profile for using a GLP-1RA." (PMID 33468131, 2021). "Consistently, a combined therapy of long-acting GLP-1 RAs and basal insulin may significantly lower HbA1c levels and reduce the risk of hypoglycaemia in patients without HF, whereas SGLT-2Is may significantly decrease HF incidence and hospitalization for HF." (PMID 33466656, 2021). "Therefore, an HbA1c target <7% is not recommended in patients with an increased risk for hypoglycemia (e.g., those treated with insulin or sulphonylureas or being in DCKD stage 4 or 5)." (PMID 34068380, 2021). "In a number of cases hypoglycemia was reported together with good blood glucose control and may have been an unintended consequence of the overall lowering of blood glucose levels that ultimately enabled insulin discontinuation." (PMID 33402226, 2021). "Additionally, in small studies in non‐NET patients, intravenous or subcutaneous octreotide was found to be effective in treating sulfonylurea‐induced hypoglycemia in the acute setting, thought to be via octreotide's inhibition of insulin release from pancreatic beta cells." (PMID 33835729, 2021).
Hypoglycemia (continued). "As their mechanism of action is independent of insulin secretion their use is associated with a low incidence of hypoglycaemia and therefore, they may be added to any background glucose-lowering treatment regimen." (PMID 33107349, 2021). "Although the rates of hypoglycemia were high in our study, they were possibly higher with the patients’ previous insulin treatment, prior to the initiation of insulin analogues, since hypoglycemia was one of the criteria for use of insulin analogues in our population." (PMID 33905628, 2021). "Also, in Saudi Arabia, unwillingness to initiate insulin therapy was investigated, which showed that the patients’ negative attitudes toward insulin therapy initiation were related to lifestyle interference, assuming insulin as the last resort, hypoglycemia, and weight gain concerns." (PMID 34712538, 2021). "Furthermore, in vivo assessment in Sprague–Dawley rats showed that CS-PGA NPs produced an increase in cumulative hypoglycemia 1.7 times greater than standard subcutaneous insulin administration, likely owing to a sustained release of insulin that was more similar to the physiological pattern." (PMID 34200068, 2021). "Thus, to use the bolus setup for induction of insulin-induced hypoglycaemia in STZ diabetic minipigs may require an initial insulin sensitivity determination in the individual animals." (PMID 33727615, 2021). "Accordingly, a time period with low doses of insulin as for diabetics with enhanced oral intake of carbohydrates and potassium to avoid hypoglycemia and/or hypokalemia, may be worth of preclinical and clinical exploration, for its effects on the post-TTS lingering morbidity." (PMID 34362223, 2021). "Furthermore, persistent C-peptide secretion and thus preserved endogenous insulin production is only associated with reduced hypoglycemia and not HbA1c." (PMID 34526306, 2021). "However, many hospitals do not allow the use of intravenous insulin drips unless it is used in intensive care units due to the risk of hypoglycemia." (PMID 33920079, 2021). "While the intra islet insulin hypothesis might be an important component of iatrogenic hypoglycemia other regulatory mechanism within the islets exist including somatostatin from the delta cells inhibiting both glucagon and insulin secretion in a paracrine fashion." (PMID 34405569, 2021). "Hypoglycemia did not appear to account for the increased risk of MACE in insulin-treated patients." (PMID 34158057, 2021). "For example, the coinfusion of C-peptide with insulin could lower the risk of complications in patients with T1D by allowing tighter glycemic control without an accompanying increase in the risk of hypoglycemia." (PMID 34003799, 2021). "Moreover, hypoglycaemia and weight gain were closely associated with insulin therapy in T2D patients, in which the lower FBG target may lead to an insulin dose increase in T2D patients, which was a risk factor for hypoglycaemia and weight gain." (PMID 34337072, 2021). "However, the methods of this study were sufficient for the intent of this report, which was to raise the consciousness in the clinical community of the potential need for more limited CHO administration to treat hypoglycemia with the use of more advanced insulin delivery systems." (PMID 33535013, 2021). "Insulin users had a higher risk of hypoglycemia (aHR [95% CI]: 3.33 [2.45–4.53]) than nonusers." (PMID 34118892, 2021). "This type of physical activity can result in late hypoglycemia, including night hypoglycemia; currently, the most effective way to prevent it is through continuous glycemic monitoring systems integrated with insulin pumps that enable automatic suspension of insulin supply." (PMID 33467392, 2021).